ERBB2 (erb-b2 receptor tyrosine kinase 2)
Diseases named in the same sentence as ERBB2 in open-access papers (continued):
Sharing a sentence is not in itself a finding about the gene and the disease.
cancer (continued). "Although ErbB-2 overexpression alone cannot transform cells, it has highly integrated roles in cellular signalling that impact on the classic ‘hallmarks’ of cancer." (PMID 14710226, 2004). "ERBB2 is upregulated in other cancers such as prostate, pancreas, colon and ovary." (PMID 12942124, 2003). "The ERBB2 gene copy numbers were estimated by real-time PCR in all cancer cells." (PMID 12942124, 2003). "For example, a DNA-based vaccine based on ErbB2, an epidermal growth factor often highly expressed in some colorectal, pancreatic, endometrial, gastric, and breast cancers, has been tested in mouse models, eliciting a more powerful anti-cancer immune response compared with controls." (PMID 40573922, 2025). "ERBB2 mutations were most prevalent in bladder (8.8%), small bowel (7.4%), urinary tract (5.9%), cervical (4.8%), and salivary gland (3.9%) cancers, whereas ERBB3 mutations were most prevalent in small bowel (5.3%), bladder (5.2%), urinary tract (4.0%), GEC (2.3%), and uterine (2.1%) cancers." (PMID 40178042, 2025). "In this way, it has been described that treatment with ErbB2 targets has deleterious effects on cardiac function in patients with cancer, but nevertheless on the other hand, recent data suggest that NRG-1β could restore cardiac function after damage to the heart." (PMID 40224962, 2025). "Furthermore, the genomic profiling of human cancers has discovered recurrent somatic mutations in ERBB2, which can occur even without gene amplifications." (PMID 39335117, 2024). "Thus, cancers that harbor NRG1 fusions may be treated with specific ERBB2/HER2 or ERBB3/HER3 or pan ERBB/HER pathway inhibitors." (PMID 38369520, 2024). "These interactions with ERBB2 could be important targets for new cancer treatments." (PMID 39684551, 2024). "However, little is known about whether and how ERBB2+ cancer cell secretomes activate and/or modify the spontaneous electrophysiological activity and the morphology of the neuronal network to support cancer progression." (PMID 38638322, 2024). "Hence, CARNIVAL was able to construct a signalling network highly enriched for HER2 signalling, including the signalling proteins MAPKs, ESR1, ERBB2, EGFR, PIK3CA and EP300, which are known to be relevant for the primary mechanism of action of lapatinib in HER2 + cancers." (PMID 37715141, 2023). "Thus, the coexpression pattern between ERBB2 and other genes, such as PGAP3, STARD3, and PNMT, may be a marker of cancer, and site mutations in the interaction anchors or dysregulation in interactions related to ERBB2 may be a new target for cancer studies." (PMID 36702236, 2023). "However, the small number of patients diagnosed with ERBB2-amplified UTUC might benefit from ERBB2-targeted cancer therapy." (PMID 37173881, 2023). "In addition, bile could be used to detect genomic alterations in BTC that are cancer-targeted therapy-related candidates, such as the ERBB2, FGFR1, FGFR2, FGFR3, KRAS, and WNT pathways." (PMID 36091112, 2022). "Furthermore, metformin inhibited matrix metalloproteinase-9 activation, decreased endogenous insulin resistance, suppressed HER2 (erbB-2) oncoprotein overexpression, improved cancer patient’s survival in type 2 diabetes, and blocked migration as well as invasion of cancer cells." (PMID 35155422, 2022).
cancer (continued). "A high-frequency ERBB2 mutation and amplification result in a poor prognosis for cancer patients, regardless of whether they have more ERBB2 gene copy numbers or not." (PMID 36172165, 2022). "Furthermore, co-amplification of PSM genes located in close proximity to one another (e.g. PSMB5 and PSMB11, 14q11.2; PSMB4 and PSMD4, 1q21.3; PSMB8 and PSMB9, 6p21.32) or known cancer drivers (e.g. co-amplification of ERBB2 and PSMB3) were also frequently amplified together." (PMID 36123629, 2022). "However, there is no solid evidence to support ERBB2 gene enrichment or deficiency in influencing the survival of cancer patients." (PMID 36172165, 2022). "Finally, the expression of ERBB2 increases and promotes cancer." (PMID 36360294, 2022). "Despite its limitations, this study is the first comprehensive analysis of ERBB2 fusions in a larger group of Chinese patients with various carcinomas, it has extended our understanding of ERBB2 fusions in solid tumors significantly and may provide more inspiration in the upcoming clinical trials." (PMID 36276102, 2022). "By combining EGFR, ERBB2, and ERBB3 protein expression in a decision tree model, we identified an association with biochemical recurrence (log rank = 25.295, p < 0.001), development of bone metastases (log rank = 23.228, p < 0.001), and cancer-specific mortality (log rank = 24.586, p < 0.001)." (PMID 33918389, 2021). "Our findings also suggest that some patients whose cancer is identified as ERBB2-negative by CISH do in fact have ERBB2-associated morphology, and thus potentially could benefit from targeted anti-ERBB2 therapy." (PMID 33597560, 2021). "It is not surprising that dysregulated ErbB2 expression is implicated in various cancers." (PMID 34743185, 2021). "Furthermore, it is shown that mice lacking functional cyclin D1 are resistant to cancer caused by the ErbB-2/HER2/neu oncogene." (PMID 34977029, 2021). "Thus, HER2-targeting therapies may select for cancer cells with fewer ERBB2 copies or lower levels of HER2 protein expression." (PMID 33886505, 2021). "Previous reports showed that extracellular E-cadherin stabilizes the LIFR/gp130 and ErbB2 (HER2)/HER3 complexes to activate STAT3 and Erk1/2 with regard to maintaining the pluripotency of ES cells and is associated with the progression of human cancer, respectively." (PMID 33572536, 2021). "Moreover, Cdc25A overexpression restored ErbB2 levels in sorafenib-treated cancer cells." (PMID 34743185, 2021). "Indeed, some cancer associate isoforms such as ALK and RASA3 were shown to play a role in cancer progression while other cancer-specific isoforms such as ERBB2 were found to have a better prognostic value then canonical ERBB2 expression." (PMID 33499898, 2021). "We used publically available data from the cancer cell line encyclopaedia (CCLE) database to search for mutations in EGFR, ERBB2, ERBB3, ERBB4, KRAS and BRAF that might predispose to a different response to anti-HER2 therapies or PI3K or MAPK pathway inhibition." (PMID 33933113, 2021). "In addition, a recent pan-cancer analysis revealed that poziotinib, an irreversible pan-ErbB family inhibitor, has broad antitumor effects in multiple ERBB2-mutant cancer types independent of the mutation location." (PMID 32366937, 2020). "Analysis of 523 cancer-relevant genes and of immune cells infiltration in primary and metastatic tissues revealed atypical genomic trajectories (TMB decrease, KRAS and SMAD4 regressive mutations), specific genetic events (ERBB2 point mutations) and scarce T-cell infiltration." (PMID 32332709, 2020).
cancer (continued). "Hence, akin to common cancer types of BC, ESR1, and ERBB2 mutations are present in a mutually exclusive manner in metastatic ILCs, and may constitute mechanisms of resistance to endocrine therapy." (PMID 33083532, 2020). "Furthermore, ErbB2 induces the overexpression of the uncoupling protein 2 (UCP2) in cancer cells." (PMID 32655416, 2020). "Interestingly, we found that mutations in this region of EGFR, BRAF, ERBB2, and MAP2K1 were mutually exclusive, which is consistent with a previous report that suggested one driver mutation is sufficient cancer initiation or development." (PMID 32757330, 2020). "In addition, the relationship between HER2 and cancer cell aggressiveness has been reported as follows: amplification of the ERBB2 gene produces an overexpression of HER2 protein that leads to cancer cell survival, growth, and proliferation through the PI3K-AKT and MAPK pathways." (PMID 32210254, 2020). "However, the role of fucosylation of ERBB2 in cancer metastasis, including ESCC, is largely unknown." (PMID 33042286, 2020). "Finally, ERBB2 expression was explored in 392 BCs from an in-house dataset, 368 primary BCs from The Cancer Genome Atlas (TCGA) dataset and 10,071 tumors representing 33 cancer types from the PanCancer TCGA dataset." (PMID 32674482, 2020). "Based on our finding of the direct relationship between actin-containing ruffles and signaling active ErbB2 homodimers, it can be speculated that the combined inhibition of the actin network and ErbB2 dimers resembles a promising therapeutic approach in cancer therapy." (PMID 32714928, 2020). "Notably, targeted knockdown of genes in the ERBB2 amplicon, including GRB7, leads to an additive effect on the decreased cell-cycle progression and cancer proliferation, emphasizing the importance of GRB7 coamplified with ERBB2 in their contribution to cancer proliferation." (PMID 31083325, 2019). "Indeed, PHLDA2 overexpression suppresses anchorage-independent cell growth and decreased PHLDA2 expression results in increased cell proliferation and reduced sensitivity to targeted agents of EGFR/ErbB2-driven cancers demonstrating functional relevance for this interaction." (PMID 29861842, 2018). "However, cancer cells remaining in the body after the primary tumor is resected could have a higher Mek/Erk activity and ErbB2 expression than the cells in the primary tumor and thus be at least partially sensitive to subsequent trastuzumab-based treatments." (PMID 29285258, 2017). "However, the molecular mechanism of ERBB2 downregulation in ERBB2-positive cancers remains obscure." (PMID 28160563, 2017). "Indeed, autophagy induced by anti-ERBB2 targeting agents like Tz and Lapatinib may allow cancer cells to survive the stress induced by the therapy." (PMID 29100552, 2017). "Therefore, experiments to investigate whether the two agents may complement each other for inhibition of ErbB1 and ErbB2 in cancer cell are warranted." (PMID 27286447, 2016). "hPEPD-G278D may inhibit these cancers by silencing both ErbB1 and ErbB2." (PMID 27286447, 2016). "Interestingly, ERBB2 is frequently co-amplified and co-expressed with neighbour genes that may play a relevant role in this cancer subtype." (PMID 27462779, 2016). "By now dissecting the mechanism of action of these potent biparatopic agents as compared with ErbB2-targeting mAbs, we could elucidate compensatory responses upon blockade of ErbB2/ErbB3, which mediate adaptive resistance in ErbB2-overexpressing cancers towards mAb treatment." (PMID 27255951, 2016).
cancer (continued). "Indeed, previous studies have suggested that human LL-37 is involved in carcinogenesis via multiple reporters, such as FPR2 (FPRL1), epidermal growth factor receptor, and ERBb2, although LL-37 and its fragments and analogs also show anticancer effects in various cancer cell lines." (PMID 26175965, 2015). "In addition to changes in their shape and size, IR imaging and statistical analyses revealed that three different cancer cell lines which have different characteristic in terms of cancer classification (ER, PgR, ERBB2 amplification) induce similar modifications of the fibroblasts IR spectra." (PMID 25390361, 2014). "Inappropriate signaling through the epidermal growth factor receptor family (EGFR1/ERBB1, ERBB2/HER2, ERBB3/HER3, and ERBB4/HER4) of receptor tyrosine kinases leads to unregulated activation of multiple downstream signaling pathways that are linked to cancer formation and progression." (PMID 25386657, 2014). "Combining natural selection, gene-based pathway analysis, and other associated analysis, we proposed that the pathway was significantly associated with PCa risk, in which the mutation of EGFR, ERBB2, PTK2, RAF1, and related SNPs in the genes might be the key link in the evolution of the cancer." (PMID 24223781, 2013). "Her2 (also known as Neu or ErbB2), a receptor tyrosine kinase belonging to the human epidermal growth factor receptor (EGFR) family that also includes EGFR/Her1, Her3, and Her4, is an important component of cell-signaling networks, and is implicated in the growth of a variety of cancers." (PMID 23878723, 2013). "Thus, ErbB2 may be a promising molecular target for cancer imaging and treatment using monoclonal antibodies and peptide-targeting vectors." (PMID 24069396, 2013). "The greater SH2 recruitment capacity of ErbB1 and ErbB2 was hypothesized to confer greater oncogenic potential to cancer cells than ErbB3 and ErbB4 given that many SH2 domains are contained in proteins that facilitate mitogenesis, cell survival, and cell motility." (PMID 22973453, 2012). "Furthermore, and most importantly, the present study may shed some light on why synergistic toxicity occurs in some cancer therapy patients treated with ErbB2 inhibitors (Herceptin) and doxorubicin." (PMID 22912742, 2012). "While it appears that an up-regulation of ErbB2 in hearts in cancer patients might initially offer protection from toxic effects of doxorubicin, long-term effects of ErbB2 over-expression, particularly when not induced as a response to doxorubicin treatment, are unknown." (PMID 22912742, 2012). "Even so, it elicits an immune tolerance that may be analogous to that of ErbB2-cancer patients." (PMID 24212954, 2011). "Our study shows that ERBB2 BCs are heterogeneous with respect to clinical, immunohistochemical and molecular factors and identifies features that may be useful in the design of therapeutical approaches of these poor prognosis cancers." (PMID 20932292, 2010). "Therefore, identification of SMRT as a downstream target of ErbB2 that plays a critical role in transcriptional regulation will help develop therapeutic agents for ErbB2-positive cancer patients, such as screening small molecule(s) that increase SMRT protein levels." (PMID 19383165, 2009). "Resistance to erbB2-directed cancer treatments is an unsolved clinical problem, and therefore we asked if Pin1 inhibition could enhance the efficacy of other signaling inhibitors that target erbB2-dependent pathways." (PMID 19077306, 2008). "All three carcinoma populations of different DI showed similar profiles with sCNA, including MYC, GNAS, BRAF amplifications and, as expected, ERBB2 high‐level amplification." (PMID 41144934, 2026). "One example of a DNA vaccine is the ERBB2 ICD plasmid-based vaccine, which targets the ERBB2 receptor commonly overexpressed in various cancers, including breast and ovarian cancers." (PMID 40160263, 2025).
cancer (continued). "More recently, the antibody-drug conjugate (ADC) fam-trastuzumab deruxtecan-nxki (T-DXd) has significantly improved outcomes in ERBB2/HER2-overexpressing and mutant cancers." (PMID 40828885, 2025). "A notable finding in this study was the cancer-type specificity observed among TACT markers, such as EPCAM and ERBB2, which displayed differential expression patterns between CRC and BC." (PMID 40003943, 2025). "Network pharmacology analysis identified 115 potential targets shared between A. racemosus phytochemicals and TNBC, revealing an involvement in key cancer-related pathways, including ERBB/ERBB2 signaling, PI3K-Akt signaling, and pathways in cancer." (PMID 40143209, 2025). "This analysis revealed upregulation of ERBB growth factor signaling to cancer cells post treatment, with increased communications received via all ERBB growth factor receptors (EGFR/ERBB1, HER2/ERBB2, HER3/ERBB3, and HER4/ERBB4)." (PMID 40341770, 2025). "Given its pivotal role in cancer progression, ERBB2 (HER2) has become a critical target for cancer therapy." (PMID 40828885, 2025). "These overlap with cancer-specific ERBB2 and nuclear ERBB4 programs, as well as the downregulation of ERBB2/ERBB4 signaling." (PMID 41009685, 2025). "We also assessed the prevalence of alterations that have been reported to impact response to HER2-directed therapies (mAb, TKI, and ADC) in ERBB2-amplified (ERBB2amp) versus ERBB2mut tumors across select cancer types." (PMID 40178042, 2025). "The largest number of disease/pathway links was found for the apoptosis-mediating FAS (n = 52) and for two cancer-related proteins, EGFR (n = 43) and ERBB2 (n = 39)." (PMID 40593564, 2025). "By leveraging RNA sequencing, network pharmacology, molecular docking, and molecular dynamics, this study has elucidated how bioactive metabolites like C3G and ursolic acid interact with key cancer-related proteins, such as PTGS2, HSP90AA1, and ERBB2." (PMID 40141751, 2025). "Other factors including lactate, cAMP, estrogen, ErbB2 and HSF-1 have been reported to influence LDHA expression and glycolysis in cancers, indicating that LDHA regulation is subtly controlled by a series of factors that need to be further investigated." (PMID 39930542, 2025). "The ERBB/ERBB2 signaling pathway and the PI3K-Akt signaling pathway are critical components in cancer biology, particularly in targeted therapies." (PMID 40143209, 2025). "The ERBB signaling pathway, mediated by ERBB receptor tyrosine kinases (ERBB-1/EGFR, ERBB-2/HER2, ERBB-3, and ERBB-4), is crucial for cellular proliferation, survival, migration, and angiogenesis, which leads to cancer progression." (PMID 40901642, 2025). "In particular, ERBB2 has been shown tophosphorylate cyclin-dependent kinase CDK1, increasing theresistance of cancer cells to apoptosis induced by the cytostaticanticancer drug paclitaxel." (PMID 41541554, 2025). "This protein promotes cancer growth and treatment resistance by activating signaling cascades involving the epidermal growth factor receptor (EGFR), erythroblastic oncogene B2 (ErbB2), and mesenchymal-epithelial transition (MET)." (PMID 39408230, 2024). "Approved antibody therapies such as trastuzumab, targeting human epidermal growth factor 2 (HER2/ERBB2), function not only by interfering with cell growth and signaling in cancer cells but also by inducing various innate immune effector processes." (PMID 38256021, 2024). "Increased NRG1 expression can activate downstream signaling pathways, such as the ERBB2/ERBB3 pathway, which promotes cancer cell proliferation, migration, and survival." (PMID 38957319, 2024). "The evaluation of FCF in cancer has just begun yet has already been found to promote the degradation of the proto-oncogenes HIF-1α and ErbB2/HER2 and to reduce HE4 expression." (PMID 38473335, 2024). "Receptor tyrosine kinases (RTKs) such as EGFR, HER2/ErbB2, MET, InsR, PDGFR, VEGFR, FGFR, EphA/B, LMR and ALK play extremely important roles in human cancers." (PMID 38245798, 2024).